BRCA1 (BRCA1 DNA repair associated)
Diseases named in the same sentence as BRCA1 in open-access papers (continued):
Sharing a sentence is not in itself a finding about the gene and the disease.
ovarian carcinoma (continued). "The current study was aimed at establishing the mutation spectrum of BRCA1/2 in the Slovenian breast/ovarian cancer families taking advantage of a complete cancer registration database." (PMID 18783588, 2008). "We assess risk management in the 3 years following BRCA1/2 mutation testing for breast and ovarian cancer risk in women and prostate and colorectal cancer risk in men." (PMID 17285126, 2007). "We studied linkage disequilibrium (LD) patterns at the BRCA1 locus, a susceptibility gene for breast and ovarian cancer, using a dense set of 114 single nucleotide polymorphisms in 5 population groups." (PMID 17916242, 2007). "For now, it is unlikely that annual gynaecological screening with TVU and CA125 will reduce mortality from ovarian cancer in BRCA1/2 mutation carriers." (PMID 17426707, 2007). "In most populations tested, the observed frequencies of BRCA1 variations in high-risk breast and/or ovarian cancer families have been described as lower than predicted by linkage analysis." (PMID 17561994, 2007). "BRCA1/2 mutation carriers have a high lifetime risk of developing ovarian cancer (39% for BRCA1, 11–22% for BRCA2 at age 70 years)." (PMID 17426707, 2007). "FA proteins are closely related to the breast/ovarian cancer susceptibility genes products BRCA1 and BRCA2, and to their partner proteins." (PMID 18047734, 2007). "Female carriers of BRCA1/2 mutations (hereafter referred to as female carriers) are at substantially increased risk of developing breast and/or ovarian cancer." (PMID 17285126, 2007). "Discussing all published studies of breast and ovarian cancer risk in BRCA1 and BRCA2 carriers is beyond the scope of this review, but we would like to address the variability of risk estimates in the literature." (PMID 17213823, 2007). "Alterations in the highly penetrant cancer susceptibility gene BRCA1 are responsible for the majority of hereditary breast and/or ovarian cancers." (PMID 17561994, 2007). "Here, we estimate selection on BRCA1 alleles leading to susceptibility to late-onset breast and ovarian cancer." (PMID 18030340, 2007). "A few hundred different mutations associated with inherited predisposition to breast and ovarian cancers have been identified in the BRCA1 and BRCA2 genes, as described at the Breast Cancer Information Core internet web site (BIC database)." (PMID 17561994, 2007). "Breast and ovarian cancer risk in BRCA1 and BRCA2 carriers is a complex trait, affected by genetic modifiers and nongenetic factors." (PMID 17213823, 2007). "Among this set, however, three displayed reduced levels in the presence of AZT: breast and ovarian cancer susceptibility (BRCA1), human homolog of double minute 2 (HDM2), and death inducer-obliterator 1 (DATF1)." (PMID 17967062, 2007). "Genetic susceptibility to breast and ovarian cancer in women arising from a mutation in the BRCA1 gene is one of the most widespread genetic diseases." (PMID 18030340, 2007). "Breast and ovarian cancers linked to mutations in BRCA1 are therefore likely to have been one of the main genetically-related causes of death in middle-aged women in past populations." (PMID 18030340, 2007). "BRCA1/2 mutation carriers are offered gynaecological screening with the intention to reduce mortality by detecting ovarian cancer at an early stage." (PMID 17426707, 2007). "In the present study we used data from French-Canadian families included in the INHERIT program to evaluate the mutation risk prediction models BOADICEA and BRCAPRO and to estimate the breast and ovarian cancer risks conferred by BRCA1 and BRCA2 mutations." (PMID 16417652, 2006).
ovarian carcinoma (continued). "The lifetime risk of carriers for developing ovarian cancer is high, 35–60% for BRCA-1 mutation carriers and 10–20% for BRCA-2 mutation carriers, in contrast to the 1.8% lifetime risk of the general population." (PMID 16495917, 2006). "Deleterious mutations in the BRCA1 gene predispose women to an increased risk of breast and ovarian cancer." (PMID 16404418, 2006). "The estimated risks for breast and ovarian cancer in BRCA1 and BRCA2 mutation carriers were consistent with previously published estimates." (PMID 16417652, 2006). "The index patients were referred because of a personal and/or family history of breast or ovarian cancer and were subsequently found to be carriers of the BRCA1: 1135insA mutation." (PMID 16509964, 2006). "We also used this data set to estimate the risks for breast and ovarian cancer conferred by BRCA1 and BRCA2 mutations." (PMID 16417652, 2006). "We also used this data set to estimate the age-specific risks for breast and ovarian cancer in BRCA1 and BRCA2 mutation carriers." (PMID 16417652, 2006). "We performed haplotype analysis of individuals from breast and ovarian cancer families from four different ethnic backgrounds who had been identified as carriers of the BRCA1: 1135insA mutation." (PMID 16509964, 2006). "In the present study we estimated breast and ovarian cancer risks conferred by BRCA1 and BRCA2 mutations in French-Canadian families." (PMID 16417652, 2006). "The biologic effects of the loss of BRCA1 gene function caused by promoter hypermethylation and by coding-region mutations in breast and ovarian cancer produce similar microarray patterns of reduced gene expression." (PMID 17047656, 2006). "Under these guidelines, full BRCA1/2 mutation screening is usually restricted to individuals affected by breast or epithelial ovarian cancer, and whose family history as a whole satisfies a ‘potentially high-risk category’." (PMID 17016486, 2006). "Based on these calculations the probability of finding one ovarian cancer in the BRCA-1 mutation carrier group was 92% and the probability of finding one ovarian cancer in the BRCA-2 mutation carrier group was 8.7%." (PMID 16495917, 2006). "Some studies have reported that ovarian cancer patients carrying germ-line BRCA1 mutations have an enhanced survival rate compared to sporadic cases." (PMID 16229746, 2005). "Mutational analysis of BRCA1/2 genes in 151 high-risk patients characterized the spectrum of gene alterations and demonstrated the dominant role of the BRCA1 c.5266dupC allele in hereditary breast and ovarian cancer." (PMID 16168118, 2005). "Almost 10% of epithelial ovarian cancer cases are associated with dominant genetic predisposition, in most cases (80 – 90%), linked to mutations in BRCA1 or BRCA2." (PMID 16229746, 2005). "About 10% of ovarian cancer patients inherit a familial predisposition, and of those cases, only 35–50% can be attributed to the inheritance of defects in the BRCA1 and BRCA2 tumor suppressor genes." (PMID 15918899, 2005). "The year 2003 brought the first direct-to-consumer advertising for an inherited breast and ovarian cancer susceptibility genetic test (BRCA1 and BRCA2)." (PMID 15888219, 2005). "Women identified as carriers of a mutation in one of the breast and ovarian cancer-susceptibility genes BRCA1 or BRCA2 have strongly elevated risks of developing breast or ovarian cancer." (PMID 16052221, 2005). "Three percent of Norwegian ovarian cancers are caused by BRCA1 1675delA or 1135insA, with a distribution similar to that found in this study." (PMID 16229746, 2005). "In the case of breast and/or ovarian cancer, the Cardiff laboratory conducts full mutation screening of all 22 relevant exons (45 fragments) of the BRCA1 gene and all 26 relevant exons (40 fragments) of the BRCA2 gene for a cancer-affected relative." (PMID 15583691, 2005).
ovarian carcinoma (continued). "Mutational analysis of BRCA1/2 genes in 151 high-risk patients characterized the spectrum of gene alterations and demonstrated the dominant role of the BRCA1 c.5266dupC (5382insC) allele in hereditary breast and ovarian cancer." (PMID 16168118, 2005). "In the present study, we used these data sources to find the frequency of the most common BRCA1 mutations in women with ovarian cancer and borderline tumours, and in the general Norwegian population." (PMID 15477862, 2004). "Overall, 31% of ovarian cancer patients and 36% of control women carried one of the two common founder mutations of BRCA1 (185 del AG or 5382 ins C) or the single common founder mutation of BRCA2 (6174 del T)." (PMID 15545966, 2004). "We found that in families with mutations occurring 5′ of BRCA1 exon 11 on average a significantly higher number of ovarian cancers were present than in families with mutations in the central portion of the gene." (PMID 15026808, 2004). "Both OC use and tubal ligation have also shown substantial protection against ovarian cancer in BRCA1 and BRCA2 mutation carriers." (PMID 15345077, 2004). "The risk of ovarian cancer conferred by a BRCA1 mutation by the age of 70 years is reported to be between 36 and 66%." (PMID 15477862, 2004). "Differences between the DA and control groups were no longer significant for the valuation of prophylactic mastectomy (P=0.13), the valuation of prophylactic oophorectomy (P=0.15), and risk accuracy of BRCA1/2 related ovarian cancer risk (P=0.18)." (PMID 14735173, 2004). "This multi-centre UK study assesses the impact of predictive testing for breast and ovarian cancer predisposition genes (BRCA1/2) in the clinical context." (PMID 15505627, 2004). "Previously, it has been reported that 3% of Norwegian ovarian cancers are caused by BRCA1 1675delA or 1135insA." (PMID 15477862, 2004). "Large differences in the BRCA1 mutation frequencies among ovarian cancer patients have been reported." (PMID 15477862, 2004). "This pattern of expression was confirmed using quantitative RT-PCR of the ARAF1 gene in a representative sample of BRCA1-associated and sporadic ovarian cancer samples." (PMID 15383145, 2004). "It should be noted that chemoprevention methods have also been modelled as presymptomatic interventions for women at increased risk of developing breast and ovarian cancer due to BRCA1/2 mutations." (PMID 15138471, 2004). "Especially, BRCA1 mutations conferred an increased risk for ovarian cancer: on average, there were nearly three times as many ovarian cancers in BRCA1 families than in BRCA2 families (0.89 vs 0.32; P=0.091)." (PMID 15026808, 2004). "In conclusion, we found reduced ovarian cancer risk associated with long-term oral contraceptive use among carriers of BRCA1 or BRCA2 mutations." (PMID 15545966, 2004). "Among the 478 ovarian cancer patients, 19 BRCA1 mutations were identified (1675delA, 1135insA, 816delGT and 3347delAG), none among the patients with borderline tumours." (PMID 15477862, 2004). "Genetic testing for the breast and ovarian cancer susceptibility genes BRCA1 and BRCA2 can help in the clinical management of individuals with family history (FH) of the disease, by identifying individuals at highest risk." (PMID 15381934, 2004). "It is well documented that the mean age at diagnosis of ovarian cancer among mutation carriers is lower than among unselected patients, and that the prevalence of BRCA1 mutations decline with increasing age at diagnosis." (PMID 15477862, 2004). "In the present seroepidemiological study, we showed that only 4% of the ovarian cancers in Norway were due to BRCA1 mutations (1675delA, 1135insA, 816delGT and 3347delAG), and none of the borderline tumours." (PMID 15477862, 2004).
ovarian carcinoma (continued). "Odds ratios (OR) of developing ovarian cancer and borderline tumours in the presence of BRCA1 mutations and CA125 level were derived from conditional logistic regression models." (PMID 15477862, 2004). "Two of the first common cancer genes to be mapped and cloned were the breast and ovarian cancer susceptibility genes BRCA1 and BRCA2." (PMID 15138471, 2004). "At the age of 70, the cumulative risk of developing ovarian cancer in a BRCA1 mutation carrier ranges from 16 to 85%, whereas the risk with a BRCA2 mutation is 10–27%." (PMID 15083174, 2004). "The frequency of BRCA1 mutations in ovarian cancer patients younger than 50 years was 7.4% (13 of 176)." (PMID 15477862, 2004). "For BRCA1, there is evidence that mutations towards the 3′ end are less likely to be associated with ovarian cancer." (PMID 12698193, 2003). "Approximately 90% of extensive breast and/or ovarian cancer families have loss of function germline mutations in the tumour suppressor genes BRCA1 or BRCA2 (17q21 and 13q12–q13, respectively)." (PMID 12698194, 2003). "Mutations within the 5′ two-thirds of BRCA1 carry a significantly higher relative risk of ovarian cancer and the same is true for mutations within the central portion of BRCA2 (the ‘OCCR’)." (PMID 12698193, 2003). "The authors of that survey noted that several UK studies have concentrated on multicase families in which ovarian cancer was prominent, thus overestimating the relative frequency of BRCA1 mutations." (PMID 12698193, 2003). "This is rarely assessed despite the fact that if women have a BRCA1 or BRCA2 mutation they are at a greatly increased lifetime risk of developing ovarian cancer." (PMID 11857010, 2002). "BRCA1 mutations have been identified in breast and ovarian cancer families from diverse ethnic backgrounds." (PMID 10682686, 2000). "Further studies will be necessary to estimate more accurately the population frequency of the BRCA1 2800delAA mutation among unselected cases of breast and ovarian cancer in Scotland and the UK." (PMID 10682686, 2000). "Truncating mutations in BRCA2 on chromosome 13q also predispose to ovarian cancer, although they confer a lower risk than mutations in BRCA1." (PMID 9579822, 1998). "The major known ovarian cancer susceptibility gene is BRCA1 on chromosome 17q, which confers a risk of approximately 60% by the age of 70 years." (PMID 9579822, 1998). "A restriction site-generating polymerase chain reaction (RG-PCR) assay was developed to detect the BRCA1 5382insC mutation that has been reported in multiple, apparently unrelated breast/ovarian carcinoma families." (PMID 9155062, 1997). "Approximately 5–15% of ovarian cancer patients harbor either germline or somatic BRCA1/2 mutations." (PMID 41493488, 2026). "For example, Lactobacillus-deficient vaginal microbiota is more common in BRCA1/2 mutation carriers and are associated with an increased risk of ovarian cancer, suggesting that oncobiosis may exacerbate the impact of genetic predispositions." (PMID 41486167, 2026). "Notably, individuals carrying BRCA1/2 mutations face a significantly elevated risk of developing ovarian cancer." (PMID 40558241, 2025). "TLK loss confers PARPi resistance in BRCA1 mutated-breast and ovarian cancer cells." (PMID 39844055, 2025). "However, the clinical outcome of women carrying BRCA1 and BRCA2 P/LP variants seems to be similar to that of patients with a single BRCA1 P/LP variant, and the probability of developing breast and ovarian cancers is comparable to those with single mutations." (PMID 39858629, 2025). "Therefore, this study aimed to evaluate the differences in survival outcomes between BRCA1/2 mutation locations, with a specific focus on exon 11, in patients with epithelial ovarian cancer." (PMID 40427158, 2025).
ovarian carcinoma (continued). "Importantly, BRCA mutations underlie hereditary breast and ovarian cancer (HBOC), and women who carry BRCA-1 pathogenic variants (mutations) have a cumulative lifetime risk of breast cancer of up to 72% and ovarian cancer of up to 72% (44%)." (PMID 41219748, 2025). "Therefore, PARP inhibitors (PARPis) are used in therapy for ovarian cancer patients with BRCA1/2 mutations, and olaparib was the first PARPi approved for therapy." (PMID 41471359, 2025). "Consequently, BRCA1/2 gene alterations are critical not only for monitoring breast and ovarian cancer risk but also for therapeutic interventions targeting these cancer types." (PMID 40859871, 2025). "One mother was found to have a known frameshift pathogenic BRCA1 variant (NM_007300.4:c.3018_3021del) relating to breast and ovarian cancer familial 1 (AD), emphasizing the need for strict regulations and consent forms to manage incidental findings and avoid delays in diagnosis." (PMID 39999070, 2025). "In Japan, the proportion of germline variants in ovarian cancer is approximately 18%, and the major genes are BRCA1, BRCA2, mismatch repair genes [MutL protein homolog (MLH) 1, MLH2, MLH6, and postmeiotic segregation increased 2], RAD51 Paralog D, and ataxia telangiectasia mutated (ATM)." (PMID 39807103, 2025). "Additionally, the cumulative risk of ovarian cancer by the age of 80 years is estimated to be 44% (95% confidence interval [CI]: 36–53%) for BRCA1 carriers and 17% (95% CI: 11–25%) for BRCA2 carriers." (PMID 40427158, 2025). "The case reports a patient with a BRCA1 mutation with a family history of breast and ovarian cancer and who developed cervical cancer then recurrent triple-negative breast cancer treated with mastectomy, radiotherapy, chemotherapy and Poly (Adenosine diphosohate-ribose) polymérase inhibitors." (PMID 40949480, 2025). "Approximately 10–15% of women with epithelial ovarian cancer carry a BRCA1 or BRCA2 mutation." (PMID 41219748, 2025). "BRCA1 mutations increase the risk of breast and ovarian cancers." (PMID 40847617, 2025). "Similarly, BRCA1/2 mutations are linked not only to breast and ovarian cancers but also to prostate and pancreatic cancers." (PMID 40599858, 2025). "RCC presents a lower prevalence of BRCA1/2 mutations than breast or ovarian cancer." (PMID 41440218, 2025). "The risk factors that were documented for ovarian cancer include a combination of genetic, lifestyle, and environmental factors, such as genetic factors and family history (mutations of BRCA1 and BRCA2 genes), fertility medication, smoking, obesity, hormonal therapy, and over‐ovulation." (PMID 40405479, 2025). "Loss of BRCA1 has been shown to be responsible for numerous tumour types, and it is linked not only with the initiation but also the progression of tumours, especially in breast and ovarian cancers." (PMID 40008534, 2025). "Overall, while the study highlights fascinating connections between ovarian cancer, the vaginal microbiota, and BRCA1 mutations, further research is necessary to determine whether changes in microbiota result from the disease or contribute to its onset." (PMID 41148804, 2025). "However, carriers showed higher rates of family and personal history of breast and ovarian cancer, as well as a higher phenotype‐based risk score for BRCA1/2 mutations (DrABC score) compared to non‐carriers (all P<0.05)." (PMID 40439693, 2025). "Consequently, mutations in BRCA1/2 genes hinder proper DNA repair and have been shown to increase the malignancy risk for hereditary cancers, especially breast and ovarian cancers." (PMID 40371388, 2025).